MUC1 (mucin 1, cell surface associated)
Diseases named in the same sentence as MUC1 in open-access papers (continued):
Sharing a sentence is not in itself a finding about the gene and the disease.
pancreatic cancer (continued). "MUC1 is particularly useful for detecting mucinous subtypes of pancreatic cancer, where the overproduction of mucins contributes to tumor progression." (PMID 39671082, 2024). "In a phase I/II study that included 48 patients with pancreatic cancer, outcomes were predicted based on baseline immunity; the patients received Wilms tumor 1 and/or MUC-1 peptide-loaded DC vaccination and standard chemotherapy." (PMID 38756774, 2024). "The most prevalent peptides to pulse DC-based vaccines for pancreatic cancer include mucin 1 (MUC1) and Wilms tumor 1 (WT1)." (PMID 39329989, 2024). "This underscores the efficacy and potential of MUC1-based immunotherapeutic strategies in pancreatic cancer treatment." (PMID 38361923, 2024). "Previous work in pancreatic cancer cells demonstrated that threonine starvation or knockdown of TARS1 decreases mucin 1 (MUC1) protein levels." (PMID 38956874, 2024). "By targeting the MUC1 glycoprotein that is overexpressed in breast, lung, ovarian, and pancreatic cancer, our nanoconjugate shows immense promise for efficient cancer therapy." (PMID 38699430, 2024). "These vaccines have been studied in relation to a range of targets of pancreatic cancer, such as MUC1, surviving, enolase 1 (ENO1), VEGFR-2, and fibroblast activation protein α-expressing cancer-associated fibroblasts (FAPα+ CAFs)." (PMID 39329989, 2024). "This study provides insights into the interplay between MUC1 and polyamine metabolism, offering potential avenues for the development of treatments against pancreatic cancer." (PMID 38547055, 2024). "Utilizing pancreatic cancer patient data, we noted a positive correlation between MUC1 expression and the expression of key polyamine metabolism pathway genes." (PMID 38547055, 2024). "In many epithelial malignancies, including breast, colon, liver, lung, ovarian, and pancreatic cancer, MUC1 is frequently overexpressed, and its intracellular activities are crucial for cell biology." (PMID 38540735, 2024). "For example, MUC1 has been shown to act as a transcriptional inducer of ABCC1 in pancreatic cancer, whereas in cervical cancer, MUC1 promotes ABCB1 expression through an EGFR-dependent mechanism." (PMID 38254882, 2024). "This is a novel mechanism of MUC1-mediated IR-resistance and will form the basis for targeting MUC1-overexpressed pancreatic cancer." (PMID 38927743, 2024). "An initial study suggested MUC-1 peptide therapy to be relatively safe in patients with pancreatic cancer; it also suggested that MUC-1 helps to enhance the immune response to tumor antigens." (PMID 38756774, 2024). "Researchers generated the ADC by conjugating HzMUC1 with MMAE, and examined the efficacy of HzMUC1-MMAE against the MUC1-positive pancreatic cancer in vitro and in vivo." (PMID 38833359, 2024). "In this study, we demonstrate that MUC1 oncogene regulates polyamine metabolism in pancreatic cancer cells." (PMID 38547055, 2024). "Our previous studies have demonstrated that MUC1 stabilizes HIF-1α transcription factor in pancreatic cancer and activates downstream signaling." (PMID 38547055, 2024). "The most prominent examples are CA125, also known as MUC16 for ovarian cancer, CA19-9 for pancreatic cancer, and KL-6 (also known as MUC1) for breast and lung cancer." (PMID 39767713, 2024). "MUC1 was previously shown to give chemoresistance in pancreatic cancer cells by upregulating multidrug resistance protein-1 (MRP1)." (PMID 38540735, 2024). "Regarding gemcitabine resistance, it was reported that HIF1α is stabilized by increased expression of MUC1 in pancreatic cancer." (PMID 38874588, 2024). "Mucin 1 (MUC1) is the first-identified mucin detected in pancreatic cancer, and its upregulation was then found in several types of solid cancers, leaving it as a candidate target for cancer therapy." (PMID 36688997, 2023).
pancreatic cancer (continued). "The aim of this study was to evaluate the in vitro characteristics of [177Lu]Lu-DOTA-C595 across pancreatic cancer cell lines with different expression of MUC1-CE to establish its feasibility as RIT for PDAC." (PMID 37578571, 2023). "A study showed that decitabine increased the expression of mucin 1 (MUC1) by demethylating DNA in pancreatic tumor cells, and decitabine was found to increase the potency of MUC1-CAR-T cells." (PMID 38201467, 2023). "The CA6 sialoglycotope of MUC1, a MUC1 epitope with limited expression on healthy tissue and overexpressed in epithelial cancers, was shown to be expressed by 76% of pancreatic cancers using the humanized antibody, huDS6." (PMID 37880707, 2023). "Our results demonstrate that targeting O-glycosylated “dynamic neoepitopes” found in the membrane-tethered MUC1 is a promising therapeutic strategy for improving the treatment outcome of patients with pancreatic cancer." (PMID 37547453, 2023). "Radioresistance is significantly aided by increased glycolysis–nucleotide metabolism, which is regulated by upregulated MUC1 in pancreatic cancer." (PMID 36831413, 2023). "Multiple MUC1-expressing tumors were analyzed in the study, including colon (33.5%), ovarian (27%), breast (9.5%), non-small cell lung cancer (9.5%), and pancreatic cancer (6.8%)." (PMID 36900282, 2023). "MUC1 expression in normal pancreas is minimal, whereas its expression is increased in approximately 90% of pancreatic cancers." (PMID 37880707, 2023). "This study used MUC1 as a marker for pancreatic tumor cells, MPO as a marker for neutrophils, and F4/80 to indicate murine macrophages." (PMID 37963142, 2023). "Mucin-1 (MUC1) is overexpressed on the surface of pancreatic tumor cells, and thus indicated tumor cells present in the sample." (PMID 37963142, 2023). "In conclusion, our HzMUC1-MMAE ADC significantly inhibits the growth of MUC1 positive pancreatic cancer cells in vitro and in vivo." (PMID 36572921, 2022). "Our results further support that HzMUC1-MMAE significantly enhances apoptosis of MUC1 positive pancreatic cancer cells." (PMID 36572921, 2022). "Upon binding, it induces an elevated cytotoxic T-lymphocyte response on tumor cells, and MUC1–chimeric antigen receptor T cells show target-specific cytotoxicity and tumor inhibition in pancreatic cancer xenograft models." (PMID 35522218, 2022). "MUC1 significantly contributes to pancreatic cancer development as it modulates the multidrug resistance genes’ expressions through both Akt-dependent and independent pathways." (PMID 35686109, 2022). "We recently generated a novel mouse monoclonal antibody specifically recognizing the human MUC1 SEA domain (MUC1-SEA Ab) with some inhibitory efficacy against pancreatic cancer in xenograft model." (PMID 36572921, 2022). "We determined that the HzMUC1 can specifically target MUC1 on the surface of pancreatic cancer cells." (PMID 36572921, 2022). "It has been reported that the MUC1 Apt has high affinity to MUC1 protein with the disassociation constant (kd) of 1.35 × 10–8 M, which has been applied in the diagnosis of pancreatic cancer." (PMID 35197099, 2022). "TRS (threonyl tRNA synthetase) controlled the synthesis of MUC1, and the TRS inhibitors, borrelidin (BN) and 5′-O-(N-(l-threonyl)-sulfamoyl)-adenosine (ThrAMS), also suppressed the migration of pancreatic cancer cells via MUC1." (PMID 36017335, 2022). "In pancreatic cancer, MUC1 reduces radiation-induced pancreatic cancer cell toxicity and DNA damage by enhancing glycolysis, the pentose phosphate pathway, and nucleotide biosynthesis." (PMID 35879749, 2022). "The well designed Apt-Tri with alleviated signal leaking including two segments: MUC1 aptamer (Apt) for the recognition of pancreatic cancer cells and the trigger (Tri) for initiating the HCR amplification." (PMID 35197099, 2022).
pancreatic cancer (continued). "Regarding mucins other than MUC1, pancreatic cancer cells become resistant to gemcitabine in parallel with MUC4 expression, and MUC13 overexpression in renal cell carcinoma was reported to play a central role in tumor progression and drug resistance." (PMID 35410995, 2022). "The glycosylation process requires the participation of many glycosyltransferases and GCNT3 is a MUC1 closely related glycosyltransferase, which was overexpressed in Kras-driven mouse and human pancreatic cancer." (PMID 35970845, 2022). "MUC1 has emerged as a potential common target for cancer therapy because it is overexpressed in a variety of different cancers including the majority of pancreatic cancer." (PMID 36572921, 2022). "Earlier work pointed out that MUC1 induced drug resistance via MUC1-C upregulation of multidrug resistance genes in pancreatic cancer cells." (PMID 35970845, 2022). "To examine if the HzMUC1 antibody recognizes MUC1 protein in pancreatic cancer cells, we performed western blot analysis with lysates from Capan-2, CFPAC-1, PANC-1, Mia-PaCa-2, PATU-8988, SW1990 cells, and hTERT-HPNE cells." (PMID 36572921, 2022). "The expression level was negatively correlated with the prognosis of pancreatic cancer patients, MUC1 (HR = 1.09, 95%CI 0.77;1.54), MUC5 (HR = 1.03, 95%CI 0.47;2.25) The expression level was not related to the prognosis of pancreatic cancer patients." (PMID 35709153, 2022). "In a variety of epithelial cancers including breast cancer and pancreatic cancer, MUC1 is often abnormally over-expressed and evenly distributed on the entire surface of cancer cells due to the loss of polar expression." (PMID 36572921, 2022). "Collectively, these experiments indicate that the efficacy of HzMUC1-MMAE against pancreatic tumors in xenograft models depends on the MUC1 level in pancreatic cancer cells." (PMID 36572921, 2022). "In summary, we have demonstrated a new and easy operating strategy in sensitive and selective detection of MUC1 overexpressed pancreatic cancer." (PMID 35197099, 2022). "In this study, we generated the antibody drug conjugate (ADC) by conjugating HzMUC1 with monomethyl auristatin (MMAE), and examined the efficacy of HzMUC1-MMAE against the MUC1-positive pancreatic cancer in vitro and in vivo." (PMID 36572921, 2022). "To further confirm, we validated the expression level of MUC1 in two cell lines: MUC1 highly expressed pancreatic cancer cell line Capan1 and MUC1 barely expressed lung cancer cell line A549." (PMID 35970845, 2022). "Our results indicate that HzMUC1-MMAE can inhibit the growth of MUC1 positive pancreatic cancer cells." (PMID 36572921, 2022). "As an essential oncogene involved in tumor progression and signaling transduction, MUC1 has been detected with high expression in numerous epithelial cancers like breast and pancreatic carcinoma." (PMID 35970845, 2022). "In pancreatic cancer, MUC1 can be detected in different stages and can indicate initiation and progression with good diagnostic accuracy." (PMID 34207342, 2021). "Tissue markers that are differentially expressed in pancreatic cancer (CEA, mucin-1 (MUC-1)), mesothelin, mutated KRAS G12, CA19-9, carcinoembryonic antigen-related cell adhesion molecule 6 (CEACAM6) have been recently studied as potentials vaccine targets." (PMID 33546207, 2021). "MUC1 as CA 15-3 is widely used as tumor marker especially in breast, ovarian, lung and pancreatic cancer." (PMID 34386419, 2021). "Based on the evidence, aberrantly overexpression of MUC1 in breast and pancreatic cancer cells drives synthesis and secretion of VEGF." (PMID 33836774, 2021). "CAR-NK cell therapy against multiple refractory solid tumors targeting mucin 1 (MUC1), including pancreatic tumors, HCC, NSCLC and triple-negative invasive breast tumors, is also under investigation in clinical trials (NCT02839954)." (PMID 34970253, 2021).
pancreatic cancer (continued). "The overexpression of MUC1 has been reported to limit the effectiveness of fluorouracil (5-FU) by reducing intracellular drug uptake and anti-tumor drug action in pancreatic tumors." (PMID 34207342, 2021). "Silencing MUC1 expression also inhibits the migration and invasion of pancreatic cancer PANC-1 cells and induces apoptosis through the downregulation of the transcription factor Slug." (PMID 34207342, 2021). "It has been remarkably reported that MUC1 facilitates a higher expression of glucose uptake and gene metabolism in pancreatic cancer models." (PMID 33836774, 2021). "The most specific IHC biomarkers consist of Galectin-1, Maspin, KOC, and S100P, whereas MUC1 is the least specific IHC biomarker for the diagnosis of pancreatic cancer in the current review." (PMID 34988027, 2021). "In the presented analysis we explored the prognostic impact of MUC1 expression in pancreatic cancer patients in the context of a controlled randomized trial with a highly characterized population with mature outcome data." (PMID 34386419, 2021). "MUC1 contributes to the growth and survival of pancreatic cancer cells by activating the MAPK pathway; pharmacological inhibition of this pathway inhibits the proliferation of MUC1-expressing cells." (PMID 34207342, 2021). "We aimed to demonstrate that low MUC1 expression is a valuable prognostic factor in pancreatic cancer patients." (PMID 34386419, 2021). "We have used two models of epithelial tumors, namely, breast and pancreatic tumors since MUC1 is present in both types therefore making it important to show that targeting the normal MUC1 on MDSCs will lead to worse prognosis." (PMID 34070449, 2021). "Certainly, the prognostic role of MUC1 in the context of resectable pancreatic cancer needs to be validated by other study groups." (PMID 34386419, 2021). "The authors performed a pyrosequencing assay for KRAS (codon 12) mutations and immunohistochemistry for MUC1/MUC2, and compared the histological diagnosis of the initial tumor and the remnant pancreatic cancer in the resected group." (PMID 33805716, 2021). "MUC1-mediated nucleotide metabolism also plays a key role in promoting radiotherapy resistance in pancreatic cancer and can inhibit effective targeting through glycolysis." (PMID 34207342, 2021). "After its initial identification in human pancreatic cancer, MUC1 expression has been detected in most epithelial cells." (PMID 34681277, 2021). "Analyses of MUC1-overexpressing cells and knockout mouse models have demonstrated that the EMT process is strongly affected by MUC1 in pancreatic cancer." (PMID 34681277, 2021). "Low MUC1 expression is significantly associated with favorable DFS and OS in patients with pancreatic cancer after curatively intended resection." (PMID 34386419, 2021). "Since the MUC-1-targeted vaccine induced antitumor immunity in murine pancreatic cancer models, its potential in inducing specific antitumor immune responses was assessed in different clinical trials." (PMID 35582441, 2020). "Increased glycolysis-nucleotide metabolism mediated by overexpressed MUC1 in pancreatic cancer also plays a key role in facilitating radioresistance." (PMID 32122374, 2020). "In the current study, MUC1 expression was strongest in malignant pancreatic tissues including all analysed pancreatic cancer types." (PMID 33379259, 2020). "The methylation status of GRAP2, ICAM3, A2ML1, MUC1, and MUC4 can influence the expression of these genes, which is associated with survival of pancreatic cancer." (PMID 33302876, 2020). "The present work demonstrates that activation of IL-17RB signaling confers pancreatic cancer cells with enhanced cancer stem-like property and resistance to gemcitabine treatment via enhanced MUC1 and MUC4 expression." (PMID 33082357, 2020). "MUC-1 is a transmembrane glycoprotein, which is highly expressed in the majority of pancreatic tumors, and that was already proposed as a therapeutic target." (PMID 32290064, 2020).
pancreatic cancer (continued). "Aiming at strategies to overcome the limitation of using EpCAM as single epitope for enrichment of CTCs, we tested both IsoFlux and KingFisher systems using different EpCAM- and Mucin1 (MUC-1)-coupled magnetic beads to enrich pancreatic tumor cells." (PMID 32290064, 2020). "To analyze the suitability of model cells for enrichment experiments, we investigated three different human pancreatic cancer cell lines for their EpCAM and MUC-1 surface expression." (PMID 32290064, 2020). "Expression of MUC1, MUC4, and MUC5AC increases progressively with the advancement of pancreatic cancer, and is associated with poor survival." (PMID 32707920, 2020). "MUC1 has been reported to be involved in upregulation of MDR genes to facilitate gemcitabine resistance in pancreatic cancer cells." (PMID 33082357, 2020). "Mucin 1(MUC1) protein, a membrane-tethered mucin glycoprotein, is also associated with poor prognosis and enhanced metastasis in human pancreatic cancers." (PMID 33005184, 2020). "They found that decitabine exposure upregulates MUC1 on the surface of pancreatic cancer cells, effectively sensitizing tumor cells to in vitro cytolysis by MUC1-specific CAR T cells." (PMID 32357417, 2020). "In pancreatic cancer, the carboxyl terminal cytoplasmic tail of MUC1 (MUC1 CT) is also demonstrated to bind to p120ctn to promote cell adhesion, motility and metastasis." (PMID 30795761, 2019). "In MUC1-expressing pancreatic cancer cells, the metabolite levels in glycolysis, PPP and nucleotide biosynthetic pathways increased to enhance the DNA damage repair and inhibit the sensibility of radiation therapy and chemotherapy." (PMID 31122265, 2019). "Similar studies have reported that MUC1 immunoreactivity can be detected in ascites samples from patients with ovarian serous carcinoma and pancreatic cancer." (PMID 31666098, 2019). "MUC1, which mediates gemcitabine resistance in pancreatic cancer, was repressed upon addition of genistein in both cell lines and this was corroborated using qPCR and western blot." (PMID 31568691, 2019). "The previous researches had indicated that Mucin1 (MUC1), an oncogene overexpressed in multiple solid tumors, can mediate DNA repair in breast cancer cells and facilitate the metabolic reprogramming in pancreatic cancer cells." (PMID 31122265, 2019). "MUC1.Tg mice bearing orthotopic KCM.Luc+ pancreatic tumors were treated with either vehicle (PBS), TAB004, or Lip-MSA-IL-2 alone or the combination of TAB004 + Lip-MSA-IL-2 weekly for up to 5 weeks (n ≥ 6 mice per treatment group)." (PMID 31114758, 2019). "As an oncogene, MUC1 is highly expressed in a variety of human adenocarcinomas, including pancreatic cancer, non-small cell lung cancer, gastric cancer and ovarian cancer." (PMID 31666098, 2019). "Targeting of other tumor antigens such as CEA (carcinoembryonic antigen), FAP, and mucin (MUC)-1 also has marked activity in murine models of pancreatic cancer." (PMID 30987642, 2019). "Meanwhile, miR-29a was found to function as tumor suppressors by targeting the MUC1 mucin in pancreatic cancer cells." (PMID 30867650, 2019). "MUC-1 has recently become an interesting target in cancer immunotherapy and it is overexpressed in nearly 90% of pancreatic cancers." (PMID 30987642, 2019). "The clinical benefit of MUC1-DCs and MUC1-CTLs was evaluated in 20 patients with unresectable or recurrent pancreatic cancer." (PMID 29946224, 2018). "By immunochemical analysis using the anti-hMUC1 monoclonal antibody, expression of MUC1 in pancreas tumor tissue was observed." (PMID 29987260, 2018). "Confocal analysis showed that the anti-hMUC1 monoclonal antibody induces the movement of MUC1 protein from the membrane into the cytoplasm effectively in both pancreatic cancer cells and xenograft tumors." (PMID 29987260, 2018). "MUC1-peptide-pulsed DCs were evaluated in the treatment of 7 patients with metastatic or recurrent pancreatic cancer." (PMID 29946224, 2018).